HOXD10 (homeobox D10)
Diseases named in the same sentence as HOXD10 in open-access papers (continued):
Sharing a sentence is not in itself a finding about the gene and the disease.
glioma (22 papers, 2012 to 2025). A benign or malignant brain and spinal cord tumor that arises from glial cells (astrocytes, oligodendrocytes, ependymal cells). "Lower expression of HOXD10 was associated with a shorter survival rate in glioma patients by Kaplan–Meier analysis using the PrognoScan database (data not shown)." (PMID 30603114, 2018). "It is conceivable that HOXD10 transcriptional upregulation and post-transcriptional suppression is indicative of a regulatory program associated with poor prognosis in glioma." (PMID 23046790, 2012). "The association between transcriptional upregulation of HOXD10 and poor survival is surprising, because HOXD10 protein levels are suppressed by a microRNA (miR-10b) highly expressed in gliomas, and it has been suggested that HOXD10 suppression by miR-10b promotes invasion." (PMID 23046790, 2012). "Since bioinformatical analysis showed that HOXD10 was a putative target of miR-23a and deregulation of HOXD10 was found to be associated with malignant tumors, we speculated that HOXD10 might be involved in the miR-23a mediated biological processes of glioma cells." (PMID 24305689, 2013). "miRNAs also influence invasion and metastasis: miR-10b enhances glioma cell invasiveness by targeting Homeobox D10 (HOXD10)." (PMID 40943278, 2025). "In a subcutaneous mouse model, gastrodin led to enhanced expression of HOXD10, induced ferroptosis of glioma cells, and suppressed glioma growth in vivo." (PMID 39062119, 2024). "Conversely, GAS demonstrated its anti-glioma impact by triggering the onset of glioma ferroptosis via the HOXD10 pathway." (PMID 39776583, 2024). "Gastrodin, a compound isolated from the orchid Gastrodia elata, is another compound capable of inducing ferroptosis in glioma cells by enhancing its main target homeobox 10 (HOXD10)." (PMID 39062119, 2024). "Based on the findings obtained from the CCK-8 assay, it was observed that the inhibition of HOXD10 effectively mitigated the 24 and 48 h suppression of glioma cell proliferation induced by gastrodin." (PMID 38138552, 2023). "In the test cohort, HOXA5, PTPN2, WT1, HOXD10, POSTN, ADAMDEC1 and MYBPH levels were elevated in glioma tissues with high-risk scores." (PMID 37812190, 2023). "To investigate this, we introduced HOXD10 siRNAs into glioma cells prior to administering the gastrodin treatment." (PMID 38138552, 2023). "Based on the results, gastrodin upregulated HOXD10, triggered ferroptosis within the analyzed cells, and suppressed glioma cell proliferation." (PMID 38138552, 2023). "Nevertheless, HOXA5, PTPN2, WT1, HOXD10, POSTN, ADAMDEC1 and MYBPH were overexpressed in ATRX-mt glioma tissues with high-risk scores compared with low-risk scores." (PMID 37812190, 2023). "The subsequent knockdown of HOXD10 significantly attenuated the impact of gastrodin on glioma cell proliferation and ferroptosis." (PMID 38138552, 2023). "We constructed a risk model using HOXA5, PTPN2, WT1, HOXD10, POSTN, ADAMDEC1 and MYBPH expression data from a cohort of patients in TCGA, and found that it had significant prognostic value for ATRX-wt glioma patients." (PMID 37812190, 2023). "In glioma tissues from the high-risk group of the training cohort, HOXA5, PTPN2, WT1, HOXD10, POSTN, ADAMDEC1 and MYBPH were highly expressed." (PMID 37812190, 2023). "A direct target of miR-10b that is likely involved in glioma invasion includes homeobox D10 (HOXD10), which negatively regulates uPAR and RhoC invasion signaling." (PMID 28698530, 2017). "Some studies have revealed that miR-10b promotes metastasis of glioma cells through regulation of HOXD10, Bim, TFAP2C, P16, and P21." (PMID 27756250, 2016). "In glioma cells HOXD10 also appears to have a tumor suppressive function as judged by repression of the invasion-related MMP-14 and uPAR genes." (PMID 25301728, 2014). "The expression of HOXD10 was significantly reduced in glioma tissues and cell lines, and miR-23a negatively regulates the protein expression of HOXD10 in U251 and U87 cells." (PMID 24305689, 2013).
glioma (continued). "HOXD10 was identified as target of miR-23a, and the expression of HOXD10 was frequently reduced in glioma tissues." (PMID 24305689, 2013). "We further identified HOXD10 as a novel miR-23a target and found that HOXD10 was frequently downregulated in glioma tissues and cell lines." (PMID 24305689, 2013). "More importantly, we found that miR-23a induced glioma cell invasion by modulating MMP-14 via its target HOXD10." (PMID 24305689, 2013). "We identified HOXD10 as a novel target of miR-23a and found that miR-23a inhibited glioma cell invasion at least partially by inhibiting the expression of HOXD10." (PMID 24305689, 2013). "The expression of HOXD10 was frequently downregulated in glioma tissues compared to their matched adjacent tissues, which correlates with the expression of miR-23a and further indicates that HOXD10 is a target of miR-23a in glioma." (PMID 24305689, 2013). "The present study showed for the first time a novel molecular mechanism of miR-23a and HOXD10 in glioma cell invasion." (PMID 24305689, 2013). "We further examined the expression of HOXD10 in glioma tissues and their matched adjacent tissues, as well as in glioma cell lines." (PMID 24305689, 2013). "Moreover, miR-10b-5p promotes glioma cell invasion by downregulating HOXD10 and upregulating invasion factors such as MMP14 and uPAR, highlighting the miR-10b-5p/HOXD10/MMP14/uPAR axis as a key driver of glioma malignancy." (PMID 39796267, 2025). "The silencing of HOXD10 resulted in the attenuation of the suppressive action of GAS on the proliferation of glioma cells, indicating that GAS may exert its anti-glioma effect by inducing the onset of glioma iron death through the HOXD10 pathway." (PMID 39776583, 2024). "Gastrodin administration significantly enhanced the expression of HOXD10 in glioma cells." (PMID 38138552, 2023). "Furthermore, the colony formation assays revealed that the silencing of HOXD10 counteracted the suppressive impact of gastrodin on the formation of colonies in glioma cells." (PMID 38138552, 2023). "Notably, gastrodin significantly upregulated HOXD10 expression in human glioma cells compared with the HT22, PC12, LO2, HPDE, NHA, HK2, and C6 cells." (PMID 38138552, 2023). "HOXD10 was significantly upregulated after treatment with gastrodin in the gliomas." (PMID 38138552, 2023). "Similarly, the 3D culture model demonstrated that the silencing of HOXD10 alleviated the suppressive effect of gastrodin on the diameters of spheres formed by glioma cells." (PMID 38138552, 2023). "Furthermore, the administration of gastrodin resulted in an elevation in HOXD10 mRNA levels within the glioma cells." (PMID 38138552, 2023). "In order to delve deeper into the transcriptional activity of HOXD10, the promoter sequences containing the wild type (Wt) and each possible binding site mutant (Mut) were inserted into the pGL4.20 plasmid and transfected into HOXD10 overexpression and control glioma cells." (PMID 38138552, 2023). "Interestingly, HOXD10 protein expression levels were higher in the glioma cell lines, including LN229, T98, and U251, relative to HT22, C6 and PC12." (PMID 38138552, 2023). "Expression of the miR-23a may also indirectly target the repressor of the matrix metallopeptidase 14 (MMP14), homeobox D10 (HOXD10), and result in glioma cell migration." (PMID 30577536, 2018). "Moreover, it promotes glioma cell proliferation via regulation of MXI1, glioma cell invasion by inhibiting the expression of HOXD10, and cell growth via targeting apoptotic protease activating factor‐1." (PMID 28248456, 2017). "Moreover, miR-23a-3p promotes the transition of colorectal cancer from the indolent to the invasive phenotype and the invasive ability of glioma cells by directly targeting HOXD10." (PMID 26110567, 2015).
glioma (continued). "In our present study, we suggest a similar regulatory mechanism of miR-23a promoting glioma cell invasion via downregulating HOXD10, which further upregulates the expression of MMP-14, a key factor implicated in extracellular matrix breakdown in physiological or pathological processes." (PMID 24305689, 2013). "The roles of miR-23a and HOXD10 in glioma cell invasion were further investigated." (PMID 24305689, 2013). "Whether other miRNAs are involved in the regulation of HOXD10 in glioma cells remains to be investigated." (PMID 24305689, 2013). "Moreover, HOXD10 was reported to be a direct target of miR-10b, which also acts as an oncogenic miRNA in glioma like miR-23a." (PMID 24305689, 2013). "Interestingly, as one of upstream regulator of IGFBP3, HoxD10 inhibits the migration and invasion of glioma and gastric cancer cells partly by modulating the expression of MMP14 and uPAR, which are both tumor invasion promoting factors." (PMID 24386080, 2013). "Therefore, the induction of HOXD10 upregulation is a strategy for glioma treatment." (PMID 38138552, 2023). "Moreover, miR-23a significantly suppressed the protein expression of HOXD10 in glioma cells." (PMID 24305689, 2013). "In glioma, it induces cell invasion by modulating MMP-14 and uPAR expression via its direct target HOXD10." (PMID 37398551, 2023). "The T cell depletion-related prognostic model was developed based on seven prognostic genes (HSPB1, HOXD10, HOXA5, SEC61G, H19, ANXA2P2, HOXC10) in glioma." (PMID 36531217, 2022). "Based on these findings, we suggest that miR-23a promotes glioma U251 cell and U87 invasion, probably by the regulation of MMP-14 via directly targeting HOXD10." (PMID 24305689, 2013). "This overexpression promoted glioma cell invasion, probably by modulating MMP-14 via directly inhibiting the expression of HOXD10, which was identified as a novel target of miR-23a." (PMID 24305689, 2013). "Furthermore, the HOXD10 mRNA expression level was lower in the normal cells LO2, HPDE, NHA, HK2, and HT22 compared with that in the glioma cell lines LN229, T98, and U251." (PMID 38138552, 2023). "In conclusion, our study revealed that an immune signature based on HOXA5, PTPN2, WT1, HOXD10, POSTN, ADAMDEC1 and MYBPH expression effectively predicted the prognosis of ATRX-wt glioma patients, and demonstrated that immunotherapy was effective for low-risk patients." (PMID 37812190, 2023). "Furthermore, RT-qPCR and Western blot analysis revealed that the enhanced transfection with HOXD10 siRNAs resulted in a decrease in both ASCL4 mRNA and protein expression in glioma cells." (PMID 38138552, 2023). "A receiver operating characteristic curve analysis indicated that HOXA5, PTPN2, WT1, HOXD10, POSTN, ADAMDEC1 and MYBPH had significant prognostic value for the survival of ATRX-wt glioma patients (AUC = 0.84, 0.81, 0.79, 0.91, 0.80, 0.79 and 0.85, respectively)." (PMID 37812190, 2023). "Accordingly, all members, but HOXD10, of the core HOX signature of IDHwt samples (i.e., upregulation of HOXA1, A5, A6, A7, A10, D9, and D10) have an oncogenic role in gliomas, by promoting cell viability and migration or by reducing cell death of GBM cell lines." (PMID 33720519, 2021). "miR-10b induces glioma cell invasion by modulating MMP-14 and uPAR expression via HOXD10." (PMID 26311318, 2015). "Specifically, DDIT3, HOXD10, PDE1C and PLS3 were upregulated in GNS cells and expressed at higher levels in glioblastomas with poor prognosis, while PTEN and TUSC3 were downregulated in GNS cells and expressed at lower levels in gliomas with poor prognosis." (PMID 23046790, 2012).
prostate carcinoma (11 papers, 2013 to 2024). A carcinoma that arises from epithelial cells of the prostate gland. "HOXD10 is upregulated in breast, gastric, hepatocellular, colorectal, bladder, and prostate cancers." (PMID 39329491, 2024). "Among these, two homeobox genes, HOXC10 and HOXD10, and TMSB15A, encoding for thymosin-beta-15A, a tumor motility gene promoting metastases in prostate cancer, all overexpressed in STCs vs LTCs." (PMID 26188123, 2015). "Examples of tumor suppressors are the homeodomain protein NKX3.1 and HOXD10 commonly down-regulated in human prostate cancer, breast tumor cells and gastric carcinogenesis." (PMID 24148231, 2013). "Hoxd10 is involved in prostate cancer processing, cell differentiation and morphogenesis." (PMID 38650655, 2024). "Reduced HOXD10 expression promotes a proliferative and aggressive phenotype of prostate cancer." (PMID 36213580, 2022). "Also the downregulation of SNAI2, ITGA3, BCL2, PGR, IGFPB3 and HOXD10 was previously reported for prostate cancer." (PMID 28005952, 2016). "HOXD10 previously was reported as downregulated in prostate cancer cells." (PMID 28005952, 2016). "Our survival analysis and the regulatory pairs with significant correlation values indicate that HOXD10 and PGR can be used as specific molecular signatures for the primary state in prostate cancer." (PMID 28005952, 2016). "Furthermore, miR224 binds to the Smad4 and Homeobox D10 (HOXD10) to promote migration of HCC and CRC while it binds to the TPD52 to inhibit migration of prostatic cancer PCa cells." (PMID 27323393, 2016). "Through the analysis of seven datasets (TCGA, GSE30521, GSE4602, GSE55945, GSE69223 GSE104131, and GSE200879), we identified two upregulated genes (AMACR and GCNT1) and seven downregulated genes (TGFB3, SRD5A2, PGM5, HOXD10, AOX1, HSPB6, and SNAI2) in prostate cancer compared to normal tissue." (PMID 38374143, 2024).
colorectal cancer (10 papers, 2015 to 2025). A primary or metastatic malignant neoplasm that affects the colon or rectum. "Follow-up studies are needed to completely evaluate HOXD10 in colorectal carcinoma, thus make detailed risk analysis and prognosis easier." (PMID 30683109, 2019). "Bioinformatics analysis revealed that HOXD10 was reduced in colorectal cancer due to hypermethylation of the HOXD10 promoter." (PMID 39858044, 2025). "HOXD10 was identified as a biological correlate of tumor suppressor DNA and an inducer of miRNA-7 and insulin-like growth factor binding protein 3 in colorectal cancer." (PMID 37812190, 2023). "In conclusion, we provide novel evidence that HOXD10 is frequently methylated, silenced, and contributes to the development of colorectal cancers." (PMID 34790580, 2021). "Many studies have shown that miR-10b inhibits homeobox D10 (HOXD10) in colorectal cancer, metastatic breast cancer, and malignant glioma cells, respectively, resulting in increased expression of RhoC." (PMID 34627249, 2021). "HOXD10 was found frequently methylated in colorectal cancer, and its hypermethylation correlates with its low expression level, advanced disease, and lymph node metastasis." (PMID 34790580, 2021). "In this research, we had uncovered that HOXD10 played a vital role in the progression of the colorectal cancer." (PMID 30683109, 2019). "The bioinformatics analysis demonstrated that HOXD10 was hypermethylated and low-expressed in colorectal cancer tissues." (PMID 30683109, 2019). "The induction of demethylation was recovered by treatment with 5-Aza-dC and the HOXD10 in colorectal cancer cell lines was re-expressed by transfection with a HOXD10 expression vector." (PMID 30683109, 2019). "The demethylation or overexpression of HOXD10 suppressed proliferation, migration, invasion and promoted apoptosis in colorectal cancer cells." (PMID 30683109, 2019). "Our findings gave an in-depth understanding of HOXD10 methylation involved in the development of colorectal cancer cell metastasis, which may serve as a possible target for therapy in times to come." (PMID 30683109, 2019). "Similarly, our study illustrated the HOXD10 hypermethylation and low mRNA expression in colorectal carcinoma tissues and cells." (PMID 30683109, 2019). "However, the biological and clinical impacts of HOXD10 overmethylation and its downstream targets in colorectal cancer remain unknown." (PMID 34790580, 2021). "Restoration of HOXD10 activates the expressions of miR-7 and IGFBP3 and results in an inhibited phenotype biologically, suggesting its potential therapeutic relevance in colorectal cancer (CRC)." (PMID 34790580, 2021). "In our study, HOXD10 was expressed at a significantly higher level in primary CRC with liver metastases than in those without liver metastases, indicating that our results favor the identification of HOXD10 as an oncogene in colorectal cancer." (PMID 28745433, 2017).
glioblastoma (10 papers, 2012 to 2025). The most malignant astrocytic tumor (WHO grade IV). "HOXD10, a member of the Abd-B homeobox gene family, has emerged as a detrimental prognostic biomarker in glioblastoma patients, aligning seamlessly with the conclusions drawn from the present investigation." (PMID 40302809, 2025). "In contrast, miRNA-23a is over-expressed in glioblastoma cells, leading to repression of the homeobox D10 (HOXD10), resulting in profound tumor invasion." (PMID 32592373, 2020). "Among these potential target genes, HOXD10 has been already proven to be a direct target of miR-10b and regulates cell proliferation in human glioblastoma cells and hepatocellular carcinoma cells." (PMID 31507632, 2019). "The miR-23a/HOXD10 pathway revealed here not only provides insight into the biology of glioblastoma but also offers a potential therapeutic target." (PMID 30603114, 2018). "Our studies demonstrated that glioblastoma cells acquire prominent invasive potential via a miR-23a-HOXD10-GMT-related pathway." (PMID 30603114, 2018). "Here, we identify miR-23a-regulated HOXD10 as a pivotal regulator of invasion in glioblastoma, providing a novel mechanism for the aggressive invasiveness of this tumor and providing insight into potential therapeutic targets." (PMID 30603114, 2018). "Together, these results suggest that miR-10 targets the expression of tumor suppressor genes, CSMD1 and HOXD10, in glioblastoma stem cells." (PMID 22558405, 2012). "At the level of individual GNS signature genes, five were significantly associated with survival (P < 0.05) in both of the two largest glioblastoma data sets we investigated (TCGA and Gravendeel): HOXD10, PDE1C, PLS3, PTEN and TUSC3." (PMID 23046790, 2012). "We showed here that the HOXD10 mRNA expression is also dramatically reduced (>20-fold) in glioblastoma stem cells examined, compared to normal neural stem cells." (PMID 22558405, 2012). "Thus, miR-23a significantly promoted invasion of glioblastoma cells with polarized formation of focal adhesions, while exogenous HOXD10 overexpression reversed these phenomena." (PMID 30603114, 2018). "Notably, the HOXD10 mRNA upregulation we observe in GNS cells also occurs in glioblastoma tumors, as shown by comparison with grade III astrocytoma." (PMID 23046790, 2012). "Among the individual signature genes, both HOXD10 and TUSC3 remained correlated with age in both data sets when limiting the analysis to IDH1 wild-type glioblastoma cases." (PMID 23046790, 2012).